OR5K1 (olfactory receptor family 5 subfamily K member 1)
Description:
Odorant receptor.
Synonyms: HTPCRX10; HSHTPCRX10; OR3-8
Tractability: Antibody: its Gene Ontology location is reachable by antibodies, with high confidence; UniProt places it where antibodies can reach, with medium confidence; UniProt predicts a signal peptide or a membrane-spanning region.
Target class: Family A G protein-coupled receptor; Membrane receptor
Gene: Protein-coding gene on chromosome 3 (98,463,201 to 98,472,924, forward strand). Ensembl gene ENSG00000232382.
Subcellular location: Cell membrane
Pathways (Reactome):
Sensory Perception: Expression and translocation of olfactory receptors; Olfactory Signaling Pathway
Gene Ontology:
Molecular function: odorant binding; olfactory receptor activity; G protein-coupled receptor activity
Biological process: sensory perception of smell; detection of chemical stimulus involved in sensory perception of smell; G protein-coupled receptor signaling pathway
Cellular component: plasma membrane; membrane
Genetic constraint (gnomAD): Loss-of-function variants: 6 observed, 10.26 expected, observed/expected ratio (o/e) 0.58, 90% interval 0.32 to 1.15. The upper end of that interval is the gene's LOEUF score, 1.15, which puts it in group 5 of 6, group 1 being the genes least tolerant of losing a copy. Missense variants: 391 observed, 337.92 expected, observed/expected ratio (o/e) 1.16, 90% interval 1.06 to 1.26. Synonymous variants: 123 observed, 118.79 expected, observed/expected ratio (o/e) 1.04, 90% interval 0.89 to 1.2.
Homologues: Orthologues: chimpanzee OR5K1 (99% identical), macaque OR5K1 (96% identical), dog OR5K1 (87% identical), mouse Or5k1 (85% identical), mouse Or5k1b (82% identical). Paralogues in human: OR5K2 (94% identical), OR5K4 (75% identical), OR5K3 (74% identical), OR5H2 (54% identical), OR5H6 (54% identical), OR5H14 (52% identical), OR5AC2 (52% identical), OR5H1 (51% identical), OR5H15 (51% identical), OR5B12 (50% identical), OR8B12 (48% identical), OR5AP2 (48% identical), and 84 more.
Diseases named in the same sentence as OR5K1 in open-access papers:
OR5K1 is named in the same sentence as 2 diseases in open-access papers, as found by Europe PMC text mining. Sharing a sentence is not in itself a finding about the gene and the disease. The quoted sentences say what the papers report.
cancer (1 paper, 2020). A tumor composed of atypical neoplastic, often pleomorphic cells that invade other tissues. "These include OR51B4 and OR5K1 genes that are over‐expressed in HCT116 cells when compared to 947 cancer cell lines." (PMID 32141232, 2020).
tumour (1 paper, 2020). "OR51B4 and OR5K1 are mostly expressed in patients with tumour grade 3 or higher." (PMID 32141232, 2020).